TSPAN4 (tetraspanin 4)
Description:
Structural component of specialized membrane microdomains known as tetraspanin-enriched microdomains (TERMs), which act as platforms for receptor clustering and signaling. Plays an essential role in migrasome formation and migration on retracting fibers at the rear end of migrating cells. Migrasomes are cellular organelles that form as large vesicle-like structures on retraction fibers of migrating cells. Mechanistically, acts as a membrane curvature sensor and participates in stabilizing the migrasome structure in a late stage of biogenesis. May also play a regulatory role for the histamine H4 receptor/HRH4 without affecting histamine binding to HRH4 or signaling.
Synonyms: Tspan-4; NAG-2; NAG2; TM4SF7; TETRASPAN
Tractability: Antibody: UniProt places it where antibodies can reach, with high confidence; its Gene Ontology location is reachable by antibodies, with high confidence; UniProt predicts a signal peptide or a membrane-spanning region. PROTAC: its protein half-life has been measured.
Gene: Protein-coding gene on chromosome 11 (840,686 to 867,120, forward strand). Ensembl gene ENSG00000214063.
Subcellular location: Cell membrane
Gene Ontology:
Molecular function: antigen binding; integrin binding; protein binding
Biological process: protein-containing complex assembly
Cellular component: focal adhesion; plasma membrane; vesicle; membrane
Genetic constraint (gnomAD): Loss-of-function variants: 38 observed, 30.78 expected, observed/expected ratio (o/e) 1.23, 90% interval 0.95 to 1.62. The synonymous counts are far from expectation, so gnomAD's model fits this gene poorly and the ratio says little. Missense variants: 325 observed, 319.27 expected, observed/expected ratio (o/e) 1.02, 90% interval 0.93 to 1.12. Synonymous variants: 185 observed, 147.53 expected, observed/expected ratio (o/e) 1.25, 90% interval 1.11 to 1.42.
Homologues: Orthologues: chimpanzee TSPAN4 (99% identical), mouse Tspan4 (94% identical), rat Tspan4 (93% identical), guinea pig TSPAN4 (92% identical), pig TSPAN4 (92% identical), macaque TSPAN4 (91% identical), dog TSPAN4 (84% identical), tropical clawed frog TSPAN4 (83% identical), zebrafish tspan4a (71% identical). Paralogues in human: TSPAN9 (56% identical), CD53 (36% identical), CD151 (34% identical), TSPAN33 (32% identical), TSPAN11 (31% identical), TSPAN8 (31% identical), CD37 (30% identical), CD63 (30% identical), TSPAN17 (30% identical), CD82 (29% identical), TSPAN5 (29% identical), TSPAN14 (29% identical), and 20 more.
Diseases named in the same sentence as TSPAN4 in open-access papers:
TSPAN4 is named in the same sentence as 40 diseases in open-access papers, as found by Europe PMC text mining. Sharing a sentence is not in itself a finding about the gene and the disease. The quoted sentences say what the papers report.
atherosclerosis (7 papers, 2022 to 2025). A disease characterized by the build-up of fatty material and calcium deposition in the arterial wall resulting in partial or complete occlusion of the arterial lumen. "For instance, TSPAN4, a tetraspanin protein essential for migrasome formation, has been shown to be highly expressed in macrophages associated with atherosclerosis regression, intraplaque hemorrhage, and plaque rupture." (PMID 40595452, 2025). "Tetraspanin 4 (TSPAN4) was highly expressed in atherosclerosis and pan-cancer, which was associated with the progression and immune cell infiltration of the tumor, especially in Glioblastoma multiforme (GBM)." (PMID 38748047, 2024). "Next, we determined the expression of TSPAN4 in atherosclerosis and pan-cancer and the prognostic and diagnostic value of TSPAN4 in pan-cancer, and the correlation between the TSPAN4 expression and immune cells were evaluated as well." (PMID 36685274, 2022). "TSPAN4 is differentially expressed in atherosclerosis and also in pan-cancer, which was associated with the progression and immune cell infiltration of the tumor, especially in GBM and GBMLGG." (PMID 36685274, 2022). "In this study, TSPAN4 expression in atherosclerosis and pan-cancer was explored and the diagnostic and prognostic value of the TSPAN4 expression as well as the immune analysis were investigated." (PMID 36685274, 2022). "Therefore, TSPAN4 may serve as a potential prognostic and diagnostic biomarker and the crosstalk between atherosclerosis and tumor progression." (PMID 36685274, 2022). "The results showed a significant upregulation of migrasome‐associated genes, including TSPAN4, TSPAN7, EOGT, and PIGK, in the model group, further supporting the high expression of migrasomes in atherosclerosis." (PMID 40548932, 2025). "This study provided a critical role of TSPAN4 aberrant expression in the progression of atherosclerosis and pan-cancer." (PMID 36685274, 2022). "TSPANs are consist of 24 family genes and involved in cancer progress, for example, TSPAN4 is regarded as a potential prognostic and immune target in glioblastoma, and it also serves as a potential biomarker and the crosstalk between atherosclerosis and tumor progression." (PMID 38725860, 2024). "The TSPAN4 mRNA and secreted protein levels were also highly expressed, which may be a potential target for migrasomes and atherosclerosis and GBM progression." (PMID 36685274, 2022). "The TSPAN4 mRNA and protein levels of the aorta root were highly expressed in atherosclerosis." (PMID 36685274, 2022). "In mouse models, TSPAN4 expression is upregulated in response to spontaneous and induced MI, suggesting that migrasomes may play a role in modulating the macrophage response during atherosclerosis progression." (PMID 40595452, 2025). "Therefore, TSPAN4 may serve as a potential biomarker and the crosstalk between atherosclerosis and tumor progression." (PMID 36685274, 2022). "Moreover, TSPAN4 is upregulated in mouse models of spontaneous myocardial infarction (MI) and induced MI, suggesting that TSPAN4 and migrasomes may be potential targets of macrophages involved in atherosclerosis." (PMID 39206093, 2024). "In this study, TSPAN4 expression was correlated to the abundance of macrophages and DC cells in GBM and GBMLGG and we still need to investigate the functions of TSPAN4 expression on patients with atherosclerosis and cancer progression." (PMID 36685274, 2022). "Targeting TSPAN4 may represent a novel therapeutic strategy for suppressing VSMC-driven vascular remodeling, potentially mitigating clinical conditions such as post-angioplasty restenosis and the progression of atherosclerosis." (PMID 41004162, 2025).
gastric cancer (7 papers, 2020 to 2024). A primary or metastatic malignant neoplasm involving the stomach. "In the current study, TSPAN4 was lowly expressed in lung cancer but highly expressed in hepatocellular carcinoma, gastric cancer and glioblastoma multiforme, and high expression of TSPAN4 was associated with lower survival rates in gastric cancer and glioblastoma multiforme." (PMID 37752917, 2023). "Once again, tobacco smoke exposure caused their induced expression and similar findings were obtained for the cell-surface protein Tspan4 which promotes cell proliferation and invasion in gastric cancers." (PMID 38245882, 2024). "Researchers have shown that the migrasome marker TSPAN4 can affect the growth of esophageal cancer, gastric cancer, glioma and liver cancer." (PMID 39206093, 2024). "The expression of TSPAN4 in gastric cancer tissues was significantly higher than that in paracancerous tissues." (PMID 36612129, 2022). "Together, TSPAN8, CD151, TSPAN1, and TSPAN4 are overexpressed in gastric cancer tissues and are related to a higher clinical stage and poorer prognosis via interacting with other molecules in TEMs." (PMID 34222025, 2021). "They demonstrated that both in vivo and in vitro, downregulation of TSPAN4 could inhibit the growth of gastric cancer cells, suggesting that TSPAN4 might play a role in slowing the progression of gastric cancer." (PMID 39206093, 2024). "The downregulation of TSPAN4 in tumor xenografts was able to suppress tumor formation, suggesting that this gene may have a retarding effect on gastric cancer progression." (PMID 36612129, 2022). "In general, the expression of TSPAN8, CD151, TSPAN1, and TSPAN4 is increased in gastric cancer tissues and enhance the proliferation and invasion of gastric cancer cells, while CD81, CD82, TSPAN5, TSPAN9, and TSPAN21 are downregulated and suppress gastric cancer cell growth." (PMID 34222025, 2021). "The role of TSPAN4 in gastric cancer was discovered through bioinformatics analysis." (PMID 34222025, 2021). "Moreover, the downregulation of TSPAN4 remarkably reduced the proliferation of gastric cancer cells." (PMID 34222025, 2021). "Therefore, TSPAN4 may be a biomarker and a potential therapeutic target for gastric cancer." (PMID 34222025, 2021). "Here, we summarize tetraspanins that enhance the proliferation and invasion of gastric cancer cells, including TSPAN8, CD151, TSPAN1, and TSPAN4." (PMID 34222025, 2021). "According to studies by DErrico and Cho, we found that the expression of TSPAN4, TSPAN9, TSPAN28, and TSPAN29 was higher in gastric cancer patients than it was in the normal population." (PMID 32694936, 2020).
glioblastoma (7 papers, 2022 to 2025). The most malignant astrocytic tumor (WHO grade IV). "Overall survival analysis of subgroups demonstrated that higher TSPAN4 expression had a worse prognosis and the univariate analysis and multivariate analysis demonstrated age, TSPAN4 expression, WHO grade, IDH status and histological types were independent risk factors of Glioblastoma multiforme." (PMID 36685274, 2022). "Using survival analysis, high TSPAN4 expression contributed to a worse prognosis in OS of GBMLGG subgroup patients, such as patients with Glioblastoma, Oligodendroglioma, Astrocytoma, WHO grade: G3, or WHO grade: G4." (PMID 36685274, 2022). "Through analyzing patients’ clinical information and genetic profiles from online databases, TIMP1, ITGA5, FCGR2B, UPP1, ISG20, TSPAN4, and LOXL1 were identified as potential prognostic biomarkers for glioblastoma." (PMID 35778451, 2022). "The relationship between Glioblastoma multiforme (GBM) and TSPAN4 was further investigated." (PMID 36685274, 2022). "We found that TIMP1, ITGA5, FCGR2B, UPP1, ISG20, TSPAN4, and LOXL1 are potential biomarkers correlated with the immune infiltration events in patients with glioblastoma." (PMID 35778451, 2022). "In addition, we used the SurvExpress analysis to further assess the prognostic value of TIMP1, ITGA5, FCGR2B, UPP1, ISG20, TSPAN4, and LOXL1 using other glioblastoma patient cohorts, including TCGA Glioblastoma and GSE4412." (PMID 35778451, 2022).
glioma (3 papers, 2023 to 2024). A benign or malignant brain and spinal cord tumor that arises from glial cells (astrocytes, oligodendrocytes, ependymal cells). "In the multivariate Cox proportional hazard regression analyses, TSPAN4 was independently associated with overall survival, suggesting that TSPAN4 may play an important role in the malignant process of glioma (HR = 1.021; 95% CI 1.005–1.037; p < 0.05)." (PMID 37587203, 2023). "Next, we used univariate and multivariate Cox regression analyses based on the CGGA dataset to determine whether TSPAN4 expression was an independent risk factor for poor prognosis in patients with glioma." (PMID 37587203, 2023). "Given the extreme correlation between TSPAN4 and glioma characteristics, we further analyzed its role in the TCGA GBMLGG cohort." (PMID 39723210, 2024). "The results showed that TSPAN4 was up-regulated in high grade glioma compared with low grade glioma in mRNAseq_325 and mRNAseq_693 cohorts." (PMID 39723210, 2024). "In glioma, TSPAN4 enhances cell proliferation and promotes macrophage polarization toward the immunosuppressive M2 phenotype." (PMID 39723210, 2024). "TSPAN4 is an independent prognostic factor and TSPAN4 knockdown has been demonstrated to strongly inhibit glioma cell proliferation, invasion, and migration in vitro." (PMID 37587203, 2023). "Western blotting confirmed that the expression of TSPAN4 was significantly higher in glioma cell lines than in normal human glial cells HMC3." (PMID 37587203, 2023). "Furthermore, our functional analysis demonstrated the influence of TSPAN4 on glioma cell proliferation, migrasome formation, and macrophage polarization, illustrating its multifaceted involvement in tumor progression and immune modulation." (PMID 39723210, 2024). "To investigate the role of TSPAN4 in glioma cells, we knocked down TSPAN4 in U87 MG glioma cells." (PMID 39723210, 2024). "Furthermore, we demonstrated that TSPAN4 promoted the proliferation of glioma cells and induced the polarization of macrophages toward the immunosuppressive M2 type." (PMID 39723210, 2024). "In addition, we examined TSPAN4's role in glioma, focusing on migrasome formation, cell proliferation, and macrophage polarization." (PMID 39723210, 2024). "Additionally, we selected TSPAN4 with the best prognostic performance for experimental validation and demonstrated that the proliferation, invasion, and migration of glioma cells were significantly inhibited after TSPAN4 knockdown." (PMID 37587203, 2023). "Subsequently, we analyzed the signaling pathways in which TSPAN4 may be involved in glioma." (PMID 39723210, 2024). "Thus, TSPAN3/11 may play a protective prognostic role, whereas TSPAN4/6/18/24/25/26/29/30 are poor prognostic factors, demonstrating that they may be potential biomarkers for glioma and serve as predictive signals for different prognoses." (PMID 37587203, 2023). "Thus, the high expression of TSPAN4 in GBM may play a vital role in the malignant progression of glioma cells and the formation of the TME, and that the migrasome is a promising mechanism." (PMID 37587203, 2023). "TSPAN4 expression correlated with immunoregulatory signatures, including chemokine, receptor, MHC, Immunoinhibitor, and Immunostimulator, in glioma." (PMID 39723210, 2024). "Correlation analysis revealed that TSPAN4 was positively correlated with ITGB1, GDF15, ITGA3 and ITGA6, and negatively correlated with CHD7, ASPDH, TMEM8B and GHITM in glioma." (PMID 39723210, 2024). "In addition, knockdown of TSPAN4 could inhibit the proliferation, migration and invasion of glioma cells, and immune correlation analysis suggested that TSPANs were related to the formation of tumor microenvironment (TME), which may affect the outcome of immunotherapy." (PMID 39206093, 2024). "Further in vitro experiments also demonstrated that TSPAN4 knockdown was followed by the downregulation of EMT marker protein expression and reduced proliferation, invasion, and migration of glioma cells." (PMID 37587203, 2023).
hepatocellular carcinoma (3 papers, 2023 to 2024). A malignant tumor that arises from hepatocytes. "In addition, TSPAN4 expression in hepatocellular carcinoma was highly correlated with tumor-associated macrophages." (PMID 37752917, 2023). "These led us to propose the hypothesis that high expression of TSPAN4 may similarly affect survival in hepatocellular carcinoma." (PMID 37752917, 2023). "Implying that TSPAN4 affected the tumor microenvironment of hepatocellular carcinoma." (PMID 37752917, 2023). "However, TSPAN4 has now demonstrated a potential correlation with hepatocellular carcinoma, and investigating the relationship between TSPAN4 and the prognosis of hepatocellular carcinoma should be a focus of research." (PMID 37752917, 2023). "In the context of Hepatocellular Carcinoma (HCC), elevated CD151 levels correspond with increased migrasome marker (TSPAN4) levels, enhancing neovascular formation and promoting metastasis." (PMID 38840183, 2024). "Obviously, the expression of TSPAN4 and its impact are not well described in detail in the current studies related to hepatocellular carcinoma." (PMID 37752917, 2023).
liver cancer (3 papers, 2024 to 2025). An epithelial or non-epithelial malignant neoplasm that arises from the liver. "A correlation analysis revealed a notable association between “CD151 & TSPAN4” across all datasets (Correlation coefficient | r |>0.4), indicating their heightened correlation in liver cancer." (PMID 38840183, 2024). "Our study revealed a significant correlation between CD151 expression and migrasome marker TSPAN4 in liver cancer, based on database analysis of clinical samples." (PMID 38840183, 2024). "To investigate the correlation between CD151 and migrasome marker TSPAN4 in liver cancer, we conducted database analysis using clinical data from HCC patients." (PMID 38840183, 2024). "TSPAN4, identified as a marker for migrasomes, emerged as a potential player in liver cancer metastasis due to its significant correlation with CD151." (PMID 38840183, 2024). "TSPAN4 serves as a migrasome marker in liver cancer, correlating with CD151 expression." (PMID 40909272, 2025). "Additionally, knocking down TSPAN4 significantly inhibited the proliferation of liver cancer cells." (PMID 39206093, 2024).
myocardial infarction (3 papers, 2023 to 2024). Gross necrosis of the myocardium, as a result of interruption of the blood supply to the area, as in coronary thrombosis. "The recent study has shown that TSPAN4 expression is highly associated with atherosclerosis regression-related macrophages, intraplaque hemorrhage as well as ruptured plaques, and is upregulated in spontaneous myocardial infarction (MI) and inducible MI mice model." (PMID 37852963, 2023).
lung adenocarcinoma (2 papers, 2020 to 2021). A carcinoma that arises from the lung and is characterized by the presence of malignant glandular epithelial cells. "The transcriptional product of TSPAN4 is a circular RNA that is upregulated in lung adenocarcinoma; circ-TSPAN4 can promote metastasis by increasing the expression of ZEB1." (PMID 34917619, 2021). "The other study indicated that circ-TSPAN4 facilitates lung adenocarcinoma metastasis by elevating ZEB1 via sponging miR-665." (PMID 33195693, 2020).
Miscarriage (2 papers, 2025 to 2026). A pregnancy that ends at a stage in which the fetus is incapable of surviving on its own, defined as the spontaneous loss of a fetus before the 22th week of pregnancy. "Multivariate logistic regression analysis by adjusting for all these variables (age, BMI, gestational days, RBC, WBC, Hb, smoking, and drinking) showed that the protein levels of MMP‐2, NDST1, and TSPAN4 were positively associated with miscarriage." (PMID 41168951, 2026). "Collectively, recovery of migrasome formation by supplement with murine Tspan4 could efficiently alleviate miscarriage in BaP‐induced mouse miscarriage model." (PMID 41168951, 2026). "To directly explore whether recovery of migrasome formation might alleviate miscarriage, we constructed a miscarriage intervention model in which a plasmid overexpressing murine Tspan4, with empty vector as control, was intraperitoneally injected into BaP‐exposed pregnant mice once per three days." (PMID 41168951, 2026). "Supplement with Pkca or Tspan4, two essential proteins for migration/invasion (MI) and MF, can efficiently treat against BPB-induced miscarriage." (PMID 41271569, 2025).
abscess (1 paper, 2024). An inflammatory process characterized by the accumulation of pus within a newly formed tissue cavity which is the result of a bacterial, fungal, or parasitic infection or the presence of a foreign body. "The suppression of EhCPs loading into EVs may lead to decreased virulence, consistent with the previous study on TSPAN4 that demonstrated TSPAN4 overexpression caused decreased abscess formation in rodents." (PMID 39361713, 2024).
autism (1 paper, 2016). Persistent deficits in social interaction and communication and interaction as well as a markedly restricted repertoire of activity and interest as well as repetitive patterns of behavior. "We analyzed the Simons Simplex Collection of 2508 parent-offspring autism trios using VARPRISM, replicating 44 genes previously implicated in autism susceptibility and identifying 20 additional candidate genes, including MYO1E, KCND3, PDCD1, DLX3, and TSPAN4 (false discovery rate < 0.3)." (PMID 27562213, 2016).